BECN1 (beclin 1)
Diseases named in the same sentence as BECN1 in open-access papers (continued):
Sharing a sentence is not in itself a finding about the gene and the disease.
Alzheimer disease (43 papers, 2010 to 2026). A progressive, neurodegenerative disease characterized by loss of function and death of nerve cells in several areas of the brain leading to loss of cognitive function such as memory and language. "In a mouse model of Alzheimer’s Disease (AD), reduced Beclin 1 expression has been shown to cause an increase in intraneuronal and extracellular amyloid beta accumulation and accelerated neurodegeneration." (PMID 36311194, 2022). "In contrast, Beclin 1 is deficient in Alzheimer's dementia and this deficiency impairs neuronal autophagy promoting neurodegeneration." (PMID 21217818, 2010). "Recently, BECN1 deficiency was shown to enhance the pathology of a mouse model of Alzheimer Disease (AD)." (PMID 20559548, 2010). "It has been shown that reduced levels of Beclin 1 are involved in the pathogenesis of Alzheimer’s disease." (PMID 40810764, 2025). "Beclin 1 is a protein molecule synthesized from neuronsand glia, and is known to play a role in the pathogenesis of some heartdiseases, Parkinson’s and Alzheimer’s diseases." (PMID 41209506, 2025). "Increased BACE1-AS showed enhanced autophagy in Alzheimer disease by targeting miR-214-3p, Beclin-1, LC3-I/LC3-II, p62, and ATG5." (PMID 38461204, 2024). "Further, BCL2 and its interaction with BECN1 regulate the clearance of amyloid β oligomers that contribute to a mouse model of Alzheimer’s disease, and impact mouse lifespan." (PMID 39602254, 2024). "We decided to evaluate serum biomarkers of neuronal injury characteristic for Alzheimer’s disease such as amyloid peptides (1-38, 1-40 and 1-42), tau protein and beclin 1, which can predict the progression of brain neurodegeneration in future." (PMID 37686098, 2023). "For example, Beclin 1 expression level was found decreased in the brain of Alzheimer’s disease (AD) patients whereas overexpression of Beclin 1 reduces the accumulation of amyloid-beta in an animal model of AD." (PMID 37023120, 2023). "In Alzheimer’s disease, the expression of Beclin-1 which is a key component in the formation of the LC3_autophagosome foci is found to be reduced." (PMID 35854300, 2022). "Although lysosomal biogenesis seems to be triggered as a compensatory response when BECN1 acetylation impairs autophagic flux, autophagosome fusion with lysosomes is compromised, contributing to Alzheimer’s disease (AD) neurodegeneration." (PMID 33828486, 2021). "To study how autophagy physiologically regulates the progression of Alzheimer’s disease (AD), we generated a new knock-in mouse model with hyperactive autophagy, by genetically disrupting the nutrient-regulated interaction between BECN1 and its inhibitor BCL2." (PMID 28806762, 2017). "We had previously used this antibody (herein termed the Beclin caspase-cleavage product (CCP) antibody) to demonstrate the caspase-cleavage of Beclin-1 within degenerating astrocytes and tangles of the Alzheimer's disease (AD) brain." (PMID 21655265, 2011). "We and others have previously shown that BECN1 is strongly and specifically reduced in affected regions of Alzheimer's disease (AD) brains." (PMID 20559548, 2010). "BECN1 acetylation in Alzheimer's disease neurodegeneration impairs the autophagic flux." (PMID 34085745, 2021). "For instance, in hippocampal CA1 and cortex regions of PS1/APP mice, a rodent model of Alzheimer's disease (AD), the nuclear concentration of Beclin 1 was detected in a large proportion of neurons, compared with the cytosolic expression of Beclin 1 in the neurons of age-matched control brain." (PMID 28383560, 2017). "Furthermore, a decrease in Beclin-1 expression has been reported in the brains of patients with Alzheimer's disease (AD) and Huntington's disease (HD)." (PMID 24949430, 2014). "Another interesting connection between Beclin 1 and Parkin might link Beclin 1 to Alzheimer’s disease (AD)." (PMID 25545884, 2014).
Alzheimer disease (continued). "In addition, it has been reported that in early Alzheimer’s disease, the expression of the autophagy-related protein Beclin 1 is significantly reduced." (PMID 23604964, 2013). "Affected brain regions of patients with Alzheimer's disease (AD) show reduced levels of Beclin-1." (PMID 21095248, 2012). "For instance, while pathological processing of amyloid precursor protein (APP) to amyloid β in Alzheimer’s disease has been implicated in disrupting autophagy via the BECN1 complex, the normal non-amyloidogenic processing of APP has been associated with neuroprotection in the retina." (PMID 33224023, 2020). "Autophagy regulatory proteins such as beclin-1, PARK 2/parkin and nuclear receptor binding factor 2 (NRBF2) are dysregulated in Alzheimer’s disease." (PMID 37627261, 2023). "Deletion of bec-1 inverts longevity in worms and a recent study demonstrated Becn1 as potential therapeutic target in Alzheimer's disease, where lack of Becn1 modulates amyloid precursor protein metabolism and promotes neurodegeneration in mice." (PMID 24381713, 2013). "The expression levels of NRBF2, along with BECN1, PIK3C3 and PIK3R4, are reduced in Alzheimer disease (AD) post mortem brains." (PMID 33459128, 2021).
cervical carcinoma (42 papers, 2012 to 2025). A carcinoma arising from either the exocervical squamous epithelium or the endocervical glandular epithelium. "Our study investigates a novel combination therapy that capitalizes on the synergistic effects of Newcastle disease virus (NDV), Everolimus (EVE), and Beclin-1 (BEC) in treating human papillomavirus-associated cervical cancers in the mouse models." (PMID 40403026, 2025). "The result also indicated that, upregulated expression of Beclin 1 are associated with improved survival of cervical cancer cases." (PMID 33311531, 2020). "Our findings highlight the potential to improve outcomes in cervical cancer associated with HPV through a multi-faceted approach incorporating NDV, Everolimus, and Beclin-1." (PMID 40403026, 2025). "It has been found that USP19 promotes cervical cancer development by reducing the ubiquitination of Beclin-1." (PMID 40280943, 2025). "Immunohistochemical staining revealed that the protein expression of TRIM21 was negatively correlated with that of NCAPH and positively correlated with that of beclin-1 in cervical cancer tissues." (PMID 39103348, 2024). "Consistent with in vitro findings, TRIM21 expression was negatively correlated with that of NCAPH, but positively with Beclin-1 in cervical cancer patients." (PMID 39103348, 2024). "In cervical cancer, Beclin-1 expression was significantly decreased in samples of malignant cervical cancer tissues compared to that in normal or cervical intraepithelial neoplasia tissues." (PMID 27527160, 2016). "The upregulation of Bcl-2 in the presence of cisplatin prompted further analysis in order to elucidate its role in cervical cancer survival and its potential interaction with Beclin-1." (PMID 26474854, 2015). "With relevance to our chemotherapy protocol, it has been reported that the transgenic overexpression of BECLIN 1 sensitizes cervical cancer cells to carboplatin and to paclitaxel by promoting apoptosis and autophagic cell death." (PMID 25136588, 2014). "In cervical cancer HeLa cells, Beclin 1 knockdown promoted the cell proliferation, but Beclin 1 overexpression enhanced the autophagy and cell death through the regulation of caspase-9 expression." (PMID 25196438, 2014). "Sun reported that the CaSki cervical cancer cell line overexpressing Beclin 1 displayed reduced proliferation and increased apoptotic sensitivity to paclitaxel." (PMID 24675697, 2014). "Therefore, combining oncolytic virotherapy as an inducer of ICD with Everolimus and Beclin-1 presents a multi-interventional approach in attempting to tackle cervical cancers." (PMID 40403026, 2025). "Therefore, this study investigates the synergistic effects of NDV, Everolimus, and Beclin-1 in a mouse model of cervical cancer to evaluate their potential as an integrated therapeutic strategy." (PMID 40403026, 2025). "Some studies have revealed that HPV infection, a known cause of cervical cancer, may induce the dysregulation of p62 and Beclin-1 and inhibit autophagy, thereby promoting cervical cancer tumorigenesis." (PMID 36313902, 2022). "In this study, we found that the level of autophagy increased significantly after STAT3 knockout or knockdown in cervical cancer cells by detecting the protein expression levels of Bcl-2 and Beclin-1, it was found that the expression of Bcl-2 decreased, while the expression of Beclin-1 increased." (PMID 35057825, 2022). "Therefore, the present study focuses on the Bcl-2–Beclin 1 complex and takes RCE-4 as a model drug to deeply clarify the molecular mechanisms underlying its anti-cervical cancer effects." (PMID 34830185, 2021). "Notably, Beclin 1 levels, as determined by immunohistochemistry, negatively correlated with cervical cancer differentiation, lymph node metastasis, recurrence, death, and histological grade, indicating the fundamental role of autophagy in cancer development." (PMID 29914057, 2018).
cervical carcinoma (continued). "Moreover, positive expression of Beclin-1 in human cervical carcinoma has benefits for patients, resulting in a better prognosis." (PMID 27527160, 2016). "Silencing of Bcl-2 upregulated Beclin-1 expression in both cervical cancer cell lines." (PMID 26474854, 2015). "Curcumin suppresses renal cell carcinoma (ACHN) and cervical cancer (SiHa) cells through the up-regulation of autophagy-related proteins, including p62, LC3B and Beclin-1." (PMID 40490812, 2025). "This research investigates the possibility of using Newcastle disease virus (NDV) along with Everolimus (EVE) and Beclin-1 (BEC) to improve immune reactions and decrease tumor development in an experimental model of HPV-related cervical cancer." (PMID 40403026, 2025). "Increased beclin‐1 expression induces BCL2 to trigger apoptosis and enhances the effect of anticancer drugs in cervical cancer." (PMID 37484971, 2023). "Another study has shown that a supernatant cultured with L. crispatus and L. rhamnosus can reduce the expression of autophagy genes ATG14, BECN1, and HPV E6 oncogene to create an anti-proliferative effect on HeLa cervical cancer cells." (PMID 35800388, 2022). "The present study focused on targeting the Bcl-2–Beclin 1 complex, which is known as the key regulator of PCD, to deeply elucidate the molecular mechanism of RCE-4 against cervical cancer." (PMID 34830185, 2021). "RAME treatment increased the mRNA levels of ATG genes (ULK1, ATG5, BECN1, ATG7, ATG12, and ATG13) dose dependently in cervical cancer cells." (PMID 31387554, 2019). "The results revealed that the expression levels of Beclin-1 and LC3B were significantly lower in cervical cancer cells when compared with those of normal cervical squamous epithelial cells, and were found to negatively correlate with hrHPV infection." (PMID 25202355, 2014). "The current study revealed that the expression levels of Beclin-1 and LC3B are significantly lower in cervical cancer tissues than in normal cervical squamous epithelial tissues, and were found to negatively correlate with hrHPV infection." (PMID 25202355, 2014). "Using the established quantum dot (QD)-based immunofluorescence histochemistry (IHC) technique, the expression of Beclin-1 and LC3B in cervical cancer and the correlation with clinicopathological parameters of cervical SCC was investigated." (PMID 25202355, 2014). "To further confirm these results, we performed immunohistochemical staining and found that TRIM21 was overexpressed in 129 patients with cervical cancer (129/220, 58.64%), NCAPH was overexpressed in 84 patients (84/220, 38.18%), and beclin-1 was overexpressed in 156 patients (156/220, 70.91%)." (PMID 39103348, 2024). "As for autophagy, BCL2L10 could bind to BECN1 that was an inducer of autophagy at BH1 or BH3 domain, reducing autophagic cell death in cervical cancer by mTor signaling pathway." (PMID 30696802, 2019). "Hence, in this study, Beclin-1 and LC3B expression in cervical cancer and precancerous lesions was evaluated." (PMID 25202355, 2014). "Moreover, ZBTB28-induced growth inhibition was reversed after abrogation of autophagy by silencing BECN1, and the treatment of CQ at the concentration that has no influence on cell viability attenuated the death of cervical cancer cells induced by ZBTB28." (PMID 33931087, 2021). "While previous data suggest that Beclin-1 does not affect the anti-apoptotic activity or localization of Bcl-2, this finding may be context and cell type-specific; these studies were performed in HeLa cervical carcinoma cells and mouse embryonic fibroblasts." (PMID 23452820, 2013). "However, the autophagy induced by RAB33A overexpression in cervical cancer cells was not inhibited by 3-methyladenine (3-MA), a PI3K inhibitor, and was independent of both Beclin1 (BECN1) and WD repeat domain, phosphoinositide interacting 2 (WIPI2)." (PMID 40000633, 2025).
diabetes (42 papers, 2013 to 2025). "Beclin-1 dysfunction has been linked to several conditions, including cancer, diabetes, and neurodegenerative illnesses." (PMID 39702603, 2024). "Despite the relevance of Beclin 1 in autophagy, only two SNPs found in the BECN1 gene have so far been associated with diabetes and Machado–Joseph disease, a neurodegenerative disorder characterized by progressive cerebellar ataxia." (PMID 33147747, 2020). "Whether this interaction plays a critical role in diabetes‐induced myocardial pathology requires further investigation using a diabetic model with appropriate mutations in the BECN1 promoter." (PMID 28643395, 2017). "Therefore, chrysin may hamper diabetes-associated mesangial cell protrusion and migration through disturbing actin dynamics by interfering with autophagy via the blockade of beclin-1 and LC3 I/II." (PMID 30634545, 2019). "Both LC3 and Beclin-1 levels were significantly reduced in the Diabetes group compared with Controls (p < 0.001 for both), indicating impaired autophagic activity." (PMID 41300451, 2025). "LC3 and Beclin-1, the key indicators of autophagic activity, were significantly reduced in the Diabetes group compared with Controls (both p < 0.001), indicating a reduction in autophagic activity." (PMID 41300451, 2025). "Spermidine treatment significantly increased LC3 (p < 0.01) and Beclin-1 (p < 0.05) compared with the Diabetes group, yet values for both markers remained lower than in Controls (p < 0.01 for each)." (PMID 41300451, 2025). "HIIT, vitamin D3 injection, and their combined treatment significantly decreased the levels of Beclin-1, Fyco-1, and cathepsin D and increased the levels of mTOR and pmTOR compared to the diabetes control group (p < 0.001)." (PMID 40144137, 2025). "An analysis of the PPI network topology concerning the 89 potential core targets pinpointed AKT, LC3A, P62, 和 Beclin-1 as the quintessential targets for quercetin’s diabetes prevention strategy." (PMID 39211336, 2024). "Investigation of the protein–protein interaction (PPI) network uncovered that AKT, LC3A, P62, 和 Beclin-1 constitute the four principal targets through which quercetin’s active components exert their therapeutic effects on diabetes." (PMID 39211336, 2024). "Mechanism studies revealed that exogenous H2S inhibited diabetes-induced autophagy through decreasing the number of autophagosomes and the expression levels of Beclin-1, Atg3, Atg5 and Atg16." (PMID 34201520, 2021). "Another cellular process affected by GABA tea in STZ-induced diabetes is autophagy as seen by decreases in related protein levels including Beclin 1, ATG7, ATG12, LC3-I, and LC3-II following treatment with GABA tea." (PMID 33041786, 2020). "To evaluate the effect of autophagy in testicular injury in diabetes mellitus, we selected the autophagy-related proteins Beclin-1, p62, and light chain 3B (LC3B) to observe changes in autophagy levels in diabetic mice after Met treatment." (PMID 31871550, 2019). "In WT mice, diabetes significantly increased the binding of beclin‐1 to Atg14L, suggesting that the cardiac levels of the beclin‐1‐Vps34‐Atg14L complex were elevated." (PMID 28643395, 2017). "Quantification of these proteins revealed an increase in both Atg5 and Beclin-1 in the retinas of diabetic mice compared to control (P = 0.03 and 0.006, respectively, 12 weeks after diabetes induction, t-test)." (PMID 26924963, 2016). "To assess the role of autophagy in DCM, we measured the expression of cardiac LC3-II and Beclin-1 after two months of diabetes." (PMID 24086665, 2013). "Current research has shown that induction of diabetes reduces Beclin-1 levels, which may reflect a decrease in ATG-1 to suppress the initiation of autophagy in cardiomyocytes." (PMID 36841820, 2023). "However, the significant increase of Beclin-1 in the diabetes group in the present study indicates AMPK-independent autophagy activation." (PMID 37764807, 2023).